MAP1B (microtubule associated protein 1B)
Diseases named in the same sentence as MAP1B in open-access papers (continued):
Sharing a sentence is not in itself a finding about the gene and the disease.
cancer (14 papers, 2013 to 2025). A tumor composed of atypical neoplastic, often pleomorphic cells that invade other tissues. "The result revealed that microtubule-associated protein 1b (MAP1B) is the most significant upregulated gene related to cancer progression." (PMID 32182788, 2020). "Based on these findings, we posit that MAP1B may be a clinically valuable diagnostic marker for early cancer detection and a promising prognostic marker." (PMID 32182788, 2020). "Further, MAP1B interacts with several other proteins associated with cancer." (PMID 32182788, 2020). "Additional mRNAs, involved in EMT and target of FMRP in cancer cells, such as Microtubule Associated Protein 1B (Mtap1b), Caveolin 2 (Cav2), Desmoplakin (Dsp), Keratin 14 (Krt14), Microphthalmia-Associated Transcription Factor (Mitf) were similarly regulated at the level of translation." (PMID 24092663, 2013). "Because enhanced invasive and metastatic potential is one of the major causes of cancer death in TNBC patients, we next evaluated the effects of MAP1B depletion on the primary invasive structure, invadopodia, in TNBC cell lines." (PMID 38353696, 2024). "The TNBC-specific expression pattern of MAP1B was remarkably similar to that of the cancer metastasis-promoting proteins, Tks5 and MT1-MMP." (PMID 38353696, 2024). "ABCC1 and MAP1B are reported gene targets of miR-9-5p that have been found to predict chemoresistance in cancer." (PMID 37081981, 2023). "Among those six RBPs, MAP1B has potential applications in evaluating comprehensive neuropathic paracancer autoantibodies, as well as chemotherapy resistance and cancer progression." (PMID 35954405, 2022). "Research aimed at decoding the functional consequences of MAP1B and signaling cross-talk with other proteins in different cancers is needed in the future." (PMID 32182788, 2020). "We also assessed MAP1B expression across various cancer types using OncomineTM Platform (Thermo Fisher, Ann Arbor, MI)." (PMID 32182788, 2020). "Several studies have demonstrated that MAP1B plays an important role in a number of cellular processes, including synaptic transmission, autophagy, and cancer." (PMID 31827401, 2019). "There are no previous reports on MAP1B in PCa, but it was demonstrated to be associated with several processes in other cancers." (PMID 36614061, 2022). "Interestingly, just as in pan-cancer, missense mutation was the dominant mutation type of key genes in COAD, and MAP1B also showed the highest missense mutation frequency." (PMID 36405685, 2022). "Data revealed a diverse expression of MAP1B in various cancers." (PMID 32182788, 2020). "Finally, the enhanced crosslinking and immunoprecipitation (eCLIP) analyses reveal that FXR1 binds with the G4-enriched mRNA targets such as AHNAK, MAP1B, AHNAK2, HUWE1, DYNC1H1 and UBR4 and controls its mRNA expression in cancer cells." (PMID 38709899, 2024).
neurological diseases (7 papers, 2015 to 2024). "Purkinje cell cytoplasmic antibody type 2 (PCA-2), identified in 2000, targets the widely distributed microtubule-associated protein 1B in the central and peripheral nervous systems, leading to diverse clinical phenotypes of neurological disorders." (PMID 39072315, 2024). "Conversely, increased levels of MAP1B are found in various human neurological diseases." (PMID 35777956, 2022). "Moreover, because MAP1B is widely distributed in the central and peripheral nervous systems, there are more clinical manifestations in PCA-2-related nervous system diseases than in other PCA-related diseases." (PMID 39072315, 2024). "Interestingly, four EMT genes (MAP1B, SNAI2, MMP2, and WNT5A) were also involved in neurological diseases, brain metastasis, and response to platinum-based chemotherapy or tyrosine–kinase inhibitors." (PMID 36553576, 2022). "Furthermore, among these EMT genes, four genes (MMP2, MAP1B, SNAI2, and WNT5A) were involved in neurologic diseases." (PMID 36553576, 2022). "Interestingly, four EMT genes (MAP1B, SNAI2, MMP2, WNT5A) are also involved in neurological diseases, in brain metastasis, and interact with platinum-based chemotherapy and tyrosine–kinase inhibitors." (PMID 36553576, 2022).
neurodegenerative disease (6 papers, 2011 to 2025). A disorder of the central nervous system characterized by gradual and progressive loss of neural tissue and neurologic function. "Similar morphological findings have also been displayed in other studies of neurodegenerative diseases accompanied by electrophysiological alterations such as latency shifts and altered amplitudes like in Map1b heterozygous mutation mice." (PMID 35720065, 2022). "MAP1b is essential for normal development of the murine nervous system and its abnormal accumulation has been linked to neurodegenerative disease." (PMID 21645326, 2011). "Depending on its cofactor, CDK5 in the brain phosphorylates targets involved in neurodegenerative diseases (e.g. Tau, MAP1B), neuronal migration (e.g. DCX), and synaptic signaling (e.g. Cav2.2, Dynamin1, NR2A, DARPP-32)." (PMID 31687929, 2019). "To the best of our knowledge, we detected MYL1 for the first time in the CSF of patients with neurodegenerative diseases, and together with MAP1B and PENK, it has not previously been linked to ALS." (PMID 40681694, 2025). "A potential role of MAP1B in the mature CNS has not been defined, but its upregulation could be associated with the presence of protein aggregates in neurodegenerative disease, proteosomal degradation and autophagy." (PMID 31990932, 2020). "The second cluster, consisting of brain and neuronal proteins such as NFL, NFM, NFH, MAP1B, MOG, and MYP0, is termed the neurodegeneration cluster due to the implication of its proteins in neurodegenerative diseases." (PMID 40681694, 2025). "As ALS is a neurodegenerative disease, we examined whether a reduction of UBQLN2 also increases MAP1B levels in neuronal cells." (PMID 35777956, 2022).
neurodevelopmental disorder (5 papers, 2015 to 2025). A behavioral and cognitive disorder with onset during the developmental period that involves impaired or aberrant development of intellectual, motor, or social functions. "Microtubule-associated protein, MAP1B, is crucial for neuronal morphogenesis and disruptions in MAP1B function are correlated with neurodevelopmental disorders." (PMID 39305956, 2024). "Expression and function of MAP1B is regulated by products of genes that when mutated, or lost, also result in neurodevelopmental disorders, including ID syndromes." (PMID 30150678, 2018). "Given the strong association between MAP1B and neurodevelopmental disorders, altered MAP1B phosphorylation could also be a causative step in the progression of DYRK1a syndromes." (PMID 39305956, 2024). "Among unrelated patients referred for clinical diagnostic testing who were found to have CNVs, we identified two patients with neurodevelopmental disorders and deletions encompassing the MYO16 gene and one patient with a deletion encompassing the MAP1B gene." (PMID 25902260, 2015). "Summary of CNVs involving KIRREL3 interacting proteins MYO16, MAP1B, and ATP1B1 in patients with neurodevelopmental disorders." (PMID 25902260, 2015).
brain disorder (2 papers, 2022 to 2023). A disease affecting the brain or part of the brain. "However, no study to date has assessed whether duplication or triplication of MAP1B directly contributes to brain disorders." (PMID 37365192, 2023).
infection (2 papers, 2007 to 2023). The state of being infected such as from the introduction of a foreign agent such as serum, vaccine, antigenic substance or organism. "Four of these animals (4321, 4323, 4324 and 338) remained intermittently PCR and MAP1-B positive in subsequent weeks suggesting persistence of infection." (PMID 17662144, 2007).
peripheral neuropathy (2 papers, 2019 to 2024). A disorder affecting the peripheral nervous system. "Also known as microtubule-associated protein 1B (MAP1B), it is associated with peripheral neuropathy, which is emerging as one of the most common clinical phenotypes." (PMID 38322089, 2024).
psychiatric disorder (1 paper, 2023). A disorder characterized by behavioral and/or psychological abnormalities, often accompanied by physical symptoms. "The discovery of MAP1B triplication in the ASD patient prompted us to investigate whether MAP1B-EE is common among neurodevelopmental and psychiatric disorders." (PMID 37365192, 2023).
MAP1B also shares sentences with these, for which no sentence is quoted: periventricular nodular heterotopia (4 papers); triple-negative breast carcinoma (3); non-small cell lung carcinoma (2); acute kidney injury (1); adenocarcinoma (1); attention deficit-hyperactivity disorder (1); bipolar disorder (1); brucellosis (1); CNS tumor (1); cognitive disorder (1); colon cancer (1); diabetes (1); encephalopathies (1); epileptic encephalopathies (1); heart failure (1); hepatocellular carcinoma (1); iron deficiency (1); microcephaly (1); migraine (1); Neurodevelopmental delay (1); polycystic ovary syndrome (1); polyradiculoneuropathy (1); renal cell carcinoma (1); spinocerebellar ataxia type 1 (1); testicular germ cell tumor (1).